CTCF (CCCTC-binding factor)
Diseases named in the same sentence as CTCF in open-access papers (continued):
Sharing a sentence is not in itself a finding about the gene and the disease.
cancer (continued). "Our data thus support the view that BORIS isoproteins can both partially replace and interfere with CTCF in germline development and cancers, in manners dependent on the nature of the specific target site." (PMID 21079786, 2010). "Aberrant CTCFL expression in cancer could thus rewire enhancer-driven gene programs by altering genome architecture while maintaining CTCF-dependent housekeeping gene expression, thereby supporting continued proliferation." (PMID 41254162, 2025). "By regulating the expression of genes implicated in metabolic reprogramming, angiogenesis, and cell survival, CTCF could potentially facilitate the resilience of cancer cells to hypoxic conditions." (PMID 40959269, 2025). "Using this protocol, we detected strong binding of CTCF to mitotic chromosomes in diploid human cells, in contrast with earlier studies in karyotypically unstable cancer cell lines, suggesting that CTCF “bookmarks” specific sites critical for maintaining genome architecture across cell divisions." (PMID 40161611, 2025). "In these tissues, tumors may rely on mechanisms involving the Brother of the Regulator of Imprinted Sites (BORIS) to activate telomerase and circumvent CTCF-mediated repression, thus ensuring the unrestricted proliferation of cancer cells." (PMID 39871386, 2025). "Results involving CTCF regulation of cancer progression may be attributed to gene transcriptional activation as well as transcriptional inhibition." (PMID 38436544, 2024). "In cancer, CTCF can play both oncogenic and anti-tumor roles." (PMID 39623397, 2024). "Finally,graded mutant perturbations provide mechanistic insight into CTCF biology and mutantspecific cancer and brain related effects." (PMID 39070636, 2024). "Reinforcing CTCF's role in tumor suppression, its absence has been connected to the upregulation of programmed death‐ligand 1 (PD‐L1), thereby facilitating the evasion of immune surveillance by cancer cells." (PMID 38374872, 2024). "Moreover, it has been reported that enhanced expression of pericentromeric repeats hSATII RNA in senescent and cancer cells traps CCCTC-binding factor (CTCF), resulting in the alteration of chromatin structure and subsequent activation of inflammatory genes." (PMID 38799442, 2024). "As the binding of CTCF depends on the methylation state of the target sequence, DNA methylation influences alternative polyadenylation in this manner, and this mechanism has been shown to result in aberrant transcriptome diversity in cancer cells." (PMID 38893242, 2024). "Subsequently, CTCF expression at mRNA and protein levels was upregulated in cancer tissues." (PMID 39506204, 2024). "Additionally, CTCFL has the capacity to compete with CTCF for a subset of binding sites in cancer cells, thereby influencing chromosome architecture and gene regulation." (PMID 39126025, 2024). "Finally, recent studies using cancer cell line have shown presence of CTCF in phase-separated condensates and their integrity requires presence of CTCF suggesting instructive function of these proteins for condensate formation." (PMID 38643244, 2024). "Considering the widespread function of CTCF sites in transcription regulation, functional interactions between CTCF and other master regulators could be potentially exploited by cancer cells as a strategy to fine-tune oncogenic gene expression." (PMID 36997534, 2023). "Therefore, CTCF-IBORIS-binding of BORIS methylation events is implicated in control regions of imprinting sites, and is significant in cancer progression." (PMID 37235839, 2023). "Therefore, it is indicated that BORIS expression was crucial in modulating cell viability in cancer cells in addition to CTCF regulation." (PMID 37235839, 2023).
cancer (continued). "Of note is a report on cancer-specific CTCF (CCCTC-binding factor) binding in various cancer types." (PMID 37283809, 2023). "Furthermore, CTCF has been proposed to regulate CDK9 recruitment at the MYC locus and has been implicated in cancer-specific transcriptional dysregulation." (PMID 36998071, 2023). "After linking the CTCF loops to the regulation of PCa-related genes, we sought to obtain a global view of the CTCF-mediated contacts between CTCF binding sites and essential cancer genes." (PMID 36997534, 2023). "The abnormal DNA repair regulated by BORIS in cancer cells might disrupt the genome stability established by CTCF." (PMID 35918747, 2022). "BORIS promotes cancer cell growth, but CTCF suppresses cell growth." (PMID 35918747, 2022). "Altogether, CTCF mediates a broad range of locus-specific interactions and gene expression regulations in normal cells, and their dysregulation can support pathologies including cancer." (PMID 35509102, 2022). "This may partly explain the appearance of transformed foci in embryonic fibroblast-derived cells of CTCF-haploinsufficient (Ctcf+/-) mice, which become exceptionally prone to developing cancer, and Ctcf-null mice are inviable beyond early embryogenesis." (PMID 35757000, 2022). "Furthermore, we confirmed that de novo methylation is precluded across cancers at CpGs lying in genomic regions enriched for TF binding signatures associated with SP1, CTCF, NRF1, GABPA, KLF9, and/or YY1." (PMID 35440061, 2022). "In the future, therefore, it is possible to explore potential molecules that regulate TAD boundaries by targeting the CTCF protein, which may have broad applications in both cancers and inherited diseases." (PMID 35509102, 2022). "Of note, CTCF has been suggested to induce drug resistance in various cancers." (PMID 35693981, 2022). "Therefore, we investigated the impact of altered CTCF levels on the invasive capacity of cells, a critical step in cancer progression." (PMID 36037342, 2022). "Therefore, we decided to further investigate this relationship by testing a range of X-ray doses on CTCF-depleted cancer cells and by elaborating on the survival data to construct a model." (PMID 35409255, 2022). "In recent years, the most extensively studied disease related to CTCF protein is cancer." (PMID 35509102, 2022). "CTCF has been reported to activate downstream gene expression in cancer." (PMID 35693981, 2022). "The mechanism by which CTCF functions in a cancer-specific manner remains poorly understood." (PMID 36589746, 2022). "Likewise, in addition to DNA mutations and epimutations in the CBS, altered protein sequences and expression levels of CTCF are related to several human disorders including cancer and neurological conditions." (PMID 35993175, 2022). "hnRNPU and CTCF have been described to regulate target genes affecting cancer development." (PMID 35954396, 2022). "As such, it is understandable that alterations of CTCF are observed in cancer and may provide selective advantages to cancer cells." (PMID 35625988, 2022). "In addition to CTCF, we identified mutations in motifs of CEBPB across many cancer types and, in particular, mutations affecting the CpG site of the motif that were attributable to the SBS1 signature." (PMID 34282050, 2021). "Nevertheless, these initial findings point to a potential involvement of disrupting CTCF loops in the development of cancer, and may be a highly interesting avenue for future studies." (PMID 34257393, 2021). "Indeed, CTCF occupancy is inversely correlated to DNA methylation of its binding sites, and this pattern resulted was altered in multiple cancer settings." (PMID 34638453, 2021). "Loss of CTCF itself can also induce DNA hypermethylation at CTCF binding sites and the fusion of TAD boundaries that establish oncogenic expression patterns and increased cancer progression." (PMID 34017357, 2021).
cancer (continued). "Concerning transcription factors, sets of the most important features are less similar to each other for different cancer types but nevertheless CTCF, GABPA, RXRA, SP1, MAX and NR2F2 are more frequently included in top features than other transcription factors." (PMID 33647036, 2021). "Persistently stressed cells have lost this CTCF function, which may facilitate the genesis of damage-induced cancer initiation and neuro-degeneration." (PMID 33411704, 2021). "Additionally, when CTCF expression is induced in cancer cell lines, it promotes a decrease in proliferation and in clonogenic capacity." (PMID 34439298, 2021). "Indeed, Ctcf hemizygous mice are prone to spontaneous and induced cancer development in many tissues demonstrating that CTCF is haploinsufficient for tumor suppression." (PMID 34381034, 2021). "It is therefore not surprising that mutations in CTCF are found in many cancers, including uterine (~25%), stomach (~7%), bladder (~6%) and breast-invasive carcinoma (~4%)." (PMID 34439298, 2021). "Additional studies will be needed to determine whether CTCF functionality is altered in this subtype of human cancers." (PMID 34381034, 2021). "It is worth noting that the large difference across cancer types on the number of lost/gained CTCF sites identified under the same statistical criteria is possibly due to the various number of available samples for different cancer types and the wide range of CTCF peak numbers across samples." (PMID 32933554, 2020). "Therefore, chromatin folding perturbations can occur at various scales, include TADs and CTCF–CTCF chromatin loops in cancer genomes and recurrently altered boundaries are generally cancer-type specific." (PMID 32024999, 2020). "A tumor‐promoting role of CTCF is also supported by studies in other cancer types." (PMID 31736271, 2020). "The multifunctional role of CTCF in cancer biology may open new avenues for novel targeted anticancer therapies." (PMID 31736271, 2020). "The variation in CTCF sites between tissues of unique origin is well-known, and our data suggest CTCF may also explain differences in hypermethylation patterns seen across diverse cancers." (PMID 32503656, 2020). "Also, our identified cancer-specific lost or gained CTCF sites are only a restricted portion in functional cancer epigenomes." (PMID 32933554, 2020). "In some studies using cancer cells, these treatments caused decreased TERT expression, which may actually be due to demethylation of a downstream CTCF repressor binding site." (PMID 33245585, 2020). "Furthermore, the cell-type specific chromatin landscape dictated by CTCF contributes to the variation in tumor suppressor and oncogene function across different tissues and cancer types." (PMID 32503656, 2020). "Various numbers of available datasets might cause the large difference on the numbers of identified lost/gained CTCF sites across cancer types." (PMID 32933554, 2020). "Since SH3PXD2A or CCR7 are reported to be involved cancer cell invasion and migration, downregulation of CTCF targets SH3PXD2A and CCR7 by SH3PXD2A-AS1 might have similar functional effects on trophoblast cells during placentation." (PMID 32719429, 2020). "Therefore, mechanistic investigation of the transcriptional circuit of CTCF-s and characterization of the biological or pathological functions, especially in cancer, of this currently reported CTCF-s short isoform will need to be addressed in the future." (PMID 30948729, 2019). "Indeed, as a function of increasing TSS or CTCF cluster strength, cancer deletions displayed an increasing enrichment for breakpoints, as well as for coverage of all but the longest quintile of deletions." (PMID 30659153, 2019). "Dysfunction of CTCF can epigenetically alter many cancer‐related genes." (PMID 30873749, 2019).
cancer (continued). "We then asked whether TAD boundaries of normal and cancer cells would exhibit CTCF enrichment, and whether genes located at the boundaries would exhibit any variation in gene expression levels when compared to those located at within-TAD regions." (PMID 30894186, 2019). "Abnormal re-expression of CTCFL in these cancer cases could have functional implications by interfering with binding of CTCF in a subset of its sites or by binding to methylated sites where CTCF may be less apt or cannot bind." (PMID 30275357, 2018). "However, CTCF haploinsufficiency can have growth-promoting effects consistent with known cancer hallmarks in the presence of additional genetic hits." (PMID 30513694, 2018). "In order to assess the relevance of our findings to the process of tumorigenesis in vivo, we asked whether CTCF-dependent cancer pathways were also activated in the transcriptomes of primary mouse and human tumors." (PMID 30086769, 2018). "It will therefore be of importance to determine whether CTCF-mediated attenuation of viral oncogene expression is disrupted in HPV-driven cancers." (PMID 30359362, 2018). "Moreover, in prostate cancer, greater BORIS/CTCF ratio was detected in cancer and metastases compared to benign tissue, and an increase in this ratio correlated with higher Gleason’s grade, positive surgical margins, and increased tumor volume." (PMID 30323717, 2018). "The mechanisms that connect CTCF haploinsufficiency with cancer have yet to be elucidated." (PMID 30513694, 2018). "Moreover, CTCFL protein is rarely expressed in cancers, in contrast to CTCF that is ubiquitously expressed." (PMID 30275357, 2018). "Taken together, these results suggest a non-trivial regulatory model at this site, which may involve channeling SE action on the DSCAM-AS1 promoter in cancer cells overexpressing ERα due to strict domain definition by CTCF." (PMID 29462945, 2018). "Taken together, these data elucidate a cooperative role for PARP1 and CTCF in regulating EBV latency and ultimately could provide insight into PARP-based therapeutics for EBV-associated cancers." (PMID 29976663, 2018). "For example, two closely-spaced CTCF/BORIS binding sites were found to be required for the activity of the promoter of the TSP50 gene, encoding a testis-specific protease aberrantly expressed in cancer." (PMID 29077515, 2018). "In a larger pan-cancer set of 4128 TCGA exomes with expression profiling, we identified mutational correlation with expression for additional elements (e.g., near GATA3, CDC6, ZNF217, and CTCF transcription factor binding sites)." (PMID 29354286, 2018). "CTCF hemizygous mice displayed dysregulation of hundreds of cancer-related genes." (PMID 30275357, 2018). "Somatic missense mutations in residues critical for CTCF ZF binding to DNA can result in selective loss of binding to some CTCF target sites, but not all, indicating the functional implications of incomplete loss of CTCF binding in cancer is unclear." (PMID 30513694, 2018). "Interestingly, dePARylated CTCF is associated in a stable protein complex with PARP-1 and NMNAT-1 in cancer cells harboring silenced tumor suppressor genes." (PMID 29029387, 2017). "Accordingly, the nature of CTCF aberrations varies in different types of cancer." (PMID 28977939, 2017). "In addition, CTCF expression correlated significantly with cancer stage (P = 0.043) and pathological differentiation (P = 0.029)." (PMID 29212169, 2017). "The BORIS/CTCFL gene, is a testis-specific CTCF paralog frequently erroneously activated in cancer, although its exact role in cancer remains unclear." (PMID 29088719, 2017). "Currently, the role of CTCF in cancer remains controversial." (PMID 28977939, 2017).
cancer (continued). "Thus, BORIS for quite some time was thought to be an alternative form of CTCF, functional only in the germline and in some cancers." (PMID 29088719, 2017). "Thus, further wet-lab experimental validation and deep computational analysis of biological consequences of CTCF involving in relationship between viral replication and cancer will be required before oncolytic reovirus therapy can be used in the clinic." (PMID 27632082, 2016). "Thus, it is likely that BORIS and CTCF co-binding there uncovered a putative regulatory role for these elements in germline and/or cancer transcription." (PMID 27588042, 2016). "The addition of BORIS to cancer cells’ chromatin constitutes a potent epimutation, as it could introduce a substantial change into CTCF’s functions." (PMID 27588042, 2016). "In addition, this polymorphism affects binding to 5 proteins implicated in cancer development (CCNT2, GATA2, TAL1, KAP1 and CTCF)." (PMID 27437873, 2016). "The presence of BORIS at the main Pol I regulatory site in rDNA, however, indicates that BORIS might be involved in ribosome biogenesis in cancer cells by virtue of co-regulating the rDNA transcription with CTCF." (PMID 27588042, 2016). "Next, we tested the effect of CTCF overexpression in cancer cells." (PMID 26833217, 2016). "Similar to cancer cells, 25 % of CTCF bound regions were co-occupied by BORIS in round spermatids." (PMID 26268681, 2015). "The fact that similar patterns of CTCF and BORIS occupancy were observed for the conserved genomic regions in both human cancer cell lines and mouse germ cells strongly indicates that CTCF and BORIS co-occupancy in cancer cells recapitulates the features of germline chromatin." (PMID 26268681, 2015). "CTCF is a highly conserved 11-zinc finger protein that is involved in many human cancers; however, the biological function of CTCF in pediatric ALL is unknown." (PMID 24393203, 2014). "CTCF levels have been found to decrease with aging and cancer." (PMID 24558376, 2014). "This suggests that CTCF, and most likely RAD21 and other factors such as REST, are driving the arrangement of nucleosomes and perhaps dictating DNA methylation patterns, offering a potential explanation for the substantial reorganization of NDRs to primarily overlap CTCF in the cancer cells." (PMID 24916973, 2014). "Our data suggest that although NDRs are mostly unique to each cell type, the genomic locations of NDRs are commonly shared between normal cells, which are predominantly at enhancers, whereas in cancer cells, NDRs are located primarily at CTCF insulator elements." (PMID 24916973, 2014). "We hypothesized that over-expression of CTCF may protect leukemic cells from apoptotic cell death or promote cancer cell proliferation." (PMID 24393203, 2014). "Indeed, germline-specific CTCFL/BORIS is aberrantly activated in many tumors and cancer cell lines, and its presence there was largely overlooked by the literature devoted to CTCF-cohesin colocalization in cancer cells of somatic origin." (PMID 25408876, 2013). "We identified 27,735, 28,662, and 27,774 cCTCF sites in recently deposited CTCF ChIP-seq from 23 cancer cell lines, 20 normal cell lines, and 19 cell lines with unknown karyotypes, respectively." (PMID 23945083, 2013). "Reports have shown that the CTCF target sites within the H19 ICR are de novo methylated in a wide range of human cancers, which would lead to prevention of CTCF binding and loss of insulator function at the maternal allele, followed by IGF2 allelic reactivation." (PMID 23023303, 2012). "Our results demonstrate that CTCF is a key component of a sub-class of gene promoters, and that its deregulation may be one of the steps leading to cancer development." (PMID 21663659, 2011). "The aberrantly activated BORIS isoproteins may play the role of a “mutant CTCF” in cancers, possibly through the competition of BORIS with CTCF." (PMID 21079786, 2010).